PRL (prolactin)
Diseases named in the same sentence as PRL in open-access papers (continued):
Sharing a sentence is not in itself a finding about the gene and the disease.
prolactinoma (continued). "In conclusion, the findings of the current study yield increasing awareness that a second trial of CAB discontinuation should be attempted in well-selected patients with prolactinomas who display normal PRL levels and tumor remnant <1 cm at low doses (≤1 mg/week)." (PMID 25699020, 2015). "However, surgical debulking of lactotroph adenoma may improve hormonal control with normalisation of PRL levels with lower postoperative doses of DAs." (PMID 35683457, 2022). "Among six prolactinomas, SRLs selective for SST5 significantly suppressed in vitro secretion of PRL in four cases, two of which were DA-resistant." (PMID 41184667, 2025). "The effect of PAS was highest in the prolactinomas with high SST5 protein expression, which confirms the role of SST5 in inhibiting PRL secretion." (PMID 41184667, 2025). "On the other hand, in a subset of prolactinomas CAB and PAS were equally effective in lowering prolactin secretion." (PMID 41184667, 2025). "In a prospective study including 101 medically and 22 surgically treated patients with prolactinoma and normal cortisol reserve, decreases in the adrenal steroid DHEA-S paralleled PRL reduction after treatment with dopamine agonist or surgery." (PMID 31847209, 2019). "Mounting evidence indicates that excess prolactin impairs cognitive function, but specific assessments of attention in patients with prolactinomas are lacking." (PMID 36581642, 2022). "In order to determine the relative expression of each Notch receptor in different tumoral lactotrope cell lines, we first performed qRT-PCR of the four Notch receptors in the rat prolactinoma MMQ cells (prolactin secreting cells) and GH3 (growth hormone and prolactin secreting cells)." (PMID 28915655, 2017). "The literature shows that the correlation between prolactinoma size and serum prolactin is not always linear, particularly in smaller prolactinoma tumors where this relationship may be less clear." (PMID 37900080, 2023). "A loss of negative dopaminergic growth control resulting from a lack of PRL action on the hypothalamus might be at the origin of prolactinoma in this model but a direct autocrine action of PRL on lactotroph cells is not excluded." (PMID 29464061, 2018). "Importantly, unlike the more common prolactinomas which are seen sporadically in aging mice, hormone staining identified GH but not PRL production by these tumors." (PMID 22174695, 2011). "In patients with persistently elevated PRL levels and lack of radiological response, alternative management strategies—including surgical resection—should be considered, especially in light of recent evidence supporting the cost-effectiveness of surgery in enclosed prolactinomas." (PMID 40995599, 2025). "Due to the possibility of mixed secretion of GH and PRL, insulin-like growth factor-1 (IGF-1) assessment is recommended for patients with PRLomas at diagnosis, while its long-term monitoring is not recommended." (PMID 38370355, 2024). "Studies on first-generation somatostatin analogues (SSAs) have shown no efficacy in the treatment of resistant prolactinomas as they bind primarily to somatostatin receptor subtype 2a (SST2a), while somatostatin receptor subtype 5 (SST5) is more important in PRL secretion." (PMID 35683457, 2022).
metabolic syndrome (56 papers, 2013 to 2026). A cluster of metabolic risk factors for CARDIOVASCULAR DISEASES and TYPE 2 DIABETES MELLITUS. "A U-shaped relationship has been seen between prolactin levels and metabolic health, with both very high and very low levels of prolactin being associated with higher risk for metabolic syndrome and T2D in humans." (PMID 41091300, 2025). "Of note, when focusing on dyslipidemia, inverse associations were found between slightly elevated PRL levels and total cholesterol, low-density lipoprotein cholesterol (LDL-C), and triglyceride levels." (PMID 39857650, 2024). "When focusing on previous data about PRL and dyslipidemia, inverse associations were found between moderately elevated PRL levels and total cholesterol, LDL-C, and triglyceride levels in cross-sectional studies." (PMID 39857650, 2024). "Low prolactin levels are associated with metabolic syndrome and T2DM, while higher prolactin levels within the normal range appear to improve insulin sensitivity." (PMID 36457554, 2022). "When only dyslipidemia is evaluated, an inverse association occurs between PRL levels and total cholesterol, LDL cholesterol, and triglyceride levels." (PMID 36213259, 2022). "Larger longitudinal studies are required to further validate the association of serum PRL with various components of metabolic syndrome in the south Indian population." (PMID 35509763, 2022). "It has been observed that platelet to lymphocyte ratio (PLR) is higher in CRC patients with the Metabolic syndrome and that PRL is associated with poorer overall survival." (PMID 35560039, 2022). "Some studies with subjects stratified based on gender did show gender-specific association between serum PRL levels and glucose-induced insulin release, cardiac remodeling, and metabolic syndrome." (PMID 28384295, 2017). "Not only is the signaling activity of prolactin associated with nervous system protective behavior, prolactin is also linked with diabetic pathology, metabolic syndrome and inflammatory conditions." (PMID 25002850, 2014). "Sustained PRL levels within the normal range are crucial for cardiometabolic health, as abnormal PRL levels might represent a risk factor for the development of metabolic syndrome and cardiovascular disease." (PMID 39078526, 2024). "Aside from that, oxytocin stimulates prolactin secretion, initiating an oxytocin–prolactin positive feedback loop, and furthermore, oxytocin modulates the dopamine–prolactin pathway and may confer risk for prolactin pathway disruption and metabolic syndrome comorbidity." (PMID 35806096, 2022). "In contrast to our results, a retrospective analysis of 840 patients with PCOS in Bangladesh reported that PRL correlated negatively with age, BMI, waist circumference and the presence of metabolic syndrome." (PMID 40362476, 2025). "Undeniably, low or suppressed PRL levels have been shown to increase the rate of metabolic syndrome." (PMID 39078526, 2024). "Recent studies have found that low PRL levels have also been shown to adversely affect weight gain, glucose, and lipid metabolism, resulting in an increased prevalence of metabolic syndrome." (PMID 39682330, 2024). "Studies show that high levels of PRL promote weight gain, obesity, metabolic syndrome, and impairment of glucose–insulin and lipid profiles." (PMID 39682330, 2024). "Several cross-sectional epidemiologic studies consistently showed that circulating prolactin levels positive correlated with increased insulin sensitivity, lower glucose and lipid levels, and lower prevalence of T2D and metabolic syndrome." (PMID 36993818, 2023). "Several cross-sectional epidemiologic studies consistently showed that circulating PRL levels positive correlated with increased insulin sensitivity, lower glucose and lipid levels, and lower prevalence of T2D and metabolic syndrome." (PMID 36993818, 2023).
metabolic syndrome (continued). "In this regard, it has been demonstrated its relationship with the atrial natriuretic peptide, prolactin, and metabolic syndrome, among others." (PMID 36935755, 2023). "Many studies showed a relationship between elevated prolactin levels and the resistance of peripheral tissues to insulin, obesity/overweight, atherogenic dyslipidemia and metabolic syndrome." (PMID 37176648, 2023). "Metabolic syndrome prevalence was higher in 61 patients with prolactinoma at baseline, especially with higher levels of serum PRL." (PMID 36704037, 2022). "As such, the correction of abnormal elevations in plasma prolactin, where it exists in metabolic syndrome patients, and the reestablishment of its normal circadian variation, is a metabolic benefit of circadian bromocriptine therapy." (PMID 34200262, 2021). "The most commonly described categories of antipsychotic AEs include extrapyramidal symptoms (EPS), sedation, weight gain or obesity, metabolic syndrome, diabetes, dyslipidemia, cardiovascular effects, increased prolactin, and sexual dysfunction." (PMID 29081922, 2017). "In more recent studies, it has been shown that even reduced levels of PRL compared to the normal range can have a negative impact on weight, glycemic profile and lipid levels, promoting an increased risk of metabolic syndrome, similarly to an excess of PRL." (PMID 38787507, 2024). "PRL level is inversely correlated with dyslipidemia which is a critical component of MetS." (PMID 39663784, 2024). "In turn, low prolactin levels have also been demonstrated to exert a detrimental effect on weight gain, glucose and lipid metabolism, thus leading to an increased prevalence of metabolic syndrome." (PMID 36237192, 2022). "Also, brain serotonergic activity and prolactin response are lower in subjects with metabolic syndrome and insulin resistant." (PMID 31277616, 2019). "Even though the authors use a large sample and longitudinal analyses do not support an association of PRL with metabolic syndrome or T2D, they only test Caucasians and a single non-fasting PRL level, which does not reflect PRL pulsatility." (PMID 27093067, 2016). "However, an excess in PRL promotes metabolic syndrome and impairs lipid profiles." (PMID 39857650, 2024). "We suspect that lower prolactin levels within the normal range may lead to dyslipidemia." (PMID 33716958, 2021). "Low serum PRL within the physiological range has a negative correlation with insulin sensitivity and plasma glucose level, and is often associated with poor metabolic outcomes of metabolic syndrome and type 2 diabetes." (PMID 32477263, 2020). "Likewise, the elevations in serum cholesterol and prolactin represent a significant adverse effect, as they could contribute to subsequent medical conditions, such as metabolic syndrome or osteoporosis, if antipsychotic therapy is administered for a prolonged period." (PMID 36359338, 2022). "It is plausible that altered levels of PRL can increase the incidence of metabolic syndrome, regardless of the presence of PCOS." (PMID 39425884, 2024). "In particular, we would like to emphasize that the primary goal is not about favoring TSS over DAs, but about controlling PRL with any means necessary to achieve a positive effect on the metabolic syndrome and BMI." (PMID 38510701, 2024). "The dopamine agonists bromocriptine and cabergoline significantly improve abnormalities in glucose profile and reduce the prevalence of metabolic syndrome in a remarkable proportion of patients, regardless of whether body weight and PRL status may change." (PMID 31191454, 2019). "Dyslipidemia (cholesterol, triglycerides, LDL-cholesterol and non-HDL cholesterol) was found in three children (3.1%); high levels of prolactin (> 500 mE/L) in four children (all of them using risperidone)." (PMID 37656290, 2025).
type 2 diabetes (55 papers, 2013 to 2026). "The present results further demonstrate an increased risk of development (incidence) of type 2 diabetes, as well as prediabetes, at even lower threshold of PRL (3 ng/ml)." (PMID 38829475, 2024). "Women with gestational diabetes with accompanying low PRL levels during pregnancy were found to have an increased risk of developing type 2 diabetes in their later life." (PMID 38700812, 2024). "In conclusion, low PRL is associated with type 2 diabetes, but discrepancy between men and women in the relationship within cohort studies requires further research." (PMID 38760578, 2024). "In cross-sectional studies, compared to individuals in the highest PRL groups, those in the lowest PRL groups had greater risk of type 2 diabetes both in men: odds ratio (OR) and 95% confidence interval = 1.86 (1.56–2.22) and in women: OR = 2.15 (1.63–2.85)." (PMID 38760578, 2024). "In conclusion, we have observed that low PRL is associated with type 2 diabetes, but discrepancy between men and women in the relationship within cohort studies deserves further research." (PMID 38760578, 2024). "In conclusion, we have for first time proposed a lower reference value for PRL of 3 ng/ml (64 mlU/l), with lower levels indicating clinical hypoprolactinemia and a strong association with type 2 diabetes." (PMID 38829475, 2024). "Evidence from existing literature suggests an association between low PRL and an increased prevalence of type 2 diabetes in both sexes, mostly from cross-sectional studies." (PMID 38760578, 2024). "In this meta-analysis of 28,300 data points, we observe that in cross-sectional studies, individuals with low PRL levels were associated with higher prevalence of type 2 diabetes in both sexes." (PMID 38760578, 2024). "It has been reported that lower serum PRL levels are associated with impaired glucose regulation and type 2 diabetes." (PMID 36526972, 2022). "Several large cohort studies among the general population have concluded that low prolactin levels are associated with metabolic disease and represent a risk factor for type 2 diabetes." (PMID 34421613, 2021). "Parameters indicative of chronic inflammation, such as high-sensitivity C-reactive protein, interleukin-6, and TNF-α, are significantly and independently associated with increased serum prolactin concentrations in type 2 diabetes, chronic kidney disease, and chronic heart failure." (PMID 40650124, 2025). "Compared to men in the highest PRL category (5-34.9 ng/ml), the adjusted risk of type 2 diabetes increased progressively in those with lower PRL levels (3-4.9 ng/ml): OR (95%CI) = 1.59 (0.93–2.71), and in those in the lowest PRL category (0.3–2.9 ng/ml): OR = 5.45 (1.78–16.62)." (PMID 38829475, 2024). "At phase-1, compared to men in the highest PRL category (5-34.9 ng/ml), the adjusted risk of type 2 diabetes was significantly greater in those with lower PRL levels (3-4.9 ng/ml): OR (95%CI) = 1.56 (1.03–2.37), and in those in the lowest PRL category (0.3–2.9 ng/ml): OR = 4.61 (1.82–11.66)." (PMID 38829475, 2024). "However, the association between low prolactin and type 2 diabetes was less pronounced in men than in women." (PMID 39456268, 2024). "Low PRL is associated with increased risk of type 2 diabetes (TSDM), particularly for females." (PMID 30917615, 2019). "Human studies with high serum PRL levels caused by antipsychotic drugs or prolactinoma suggested that increased levels of PRL may have adverse metabolic effects leading to type 2 diabetes." (PMID 28384295, 2017). "Our findings suggest that a PRL level below 3 ng/ml (64 mlU/l) significantly identifies European men with a clinically-important outcome (of type 2 diabetes), offering a lower reference-value for research and clinical practice." (PMID 38829475, 2024).
type 2 diabetes (continued). "The incidences of type 2 diabetes at phase-2 examination in men with phase-1 PRL levels of 5-34.9 ng/ml (considered the normal range), 3-4.9 ng/ml, and 0.3–2.9 ng/ml were 6.3%, 9.3% and 22.7%, respectively." (PMID 38829475, 2024). "With the additional studies published more recently, we have here generated an updated meta-analysis to examine the relationship between low levels of PRL and type 2 diabetes." (PMID 38760578, 2024). "Therefore although the source studies included adjustment for age, there might remain possible residual confounding of the relationship between PRL and type 2 diabetes from very strong association between type 2 diabetes and age, if that association with age is not linear." (PMID 38760578, 2024). "We conducted a meta-analysis to examine the relationship between low PRL levels and type 2 diabetes." (PMID 38760578, 2024). "Influencing factors of prolactin (PRL) levels in include patients with type 2 diabetes (T2DM): multiple linear regression model." (PMID 36816406, 2023). "There was little data in polycystic ovary syndrome or type 2 diabetes pregnancy, but prolactin increment across pregnancy in polycystic ovary syndrome emerged as an area for future study." (PMID 36769162, 2023). "KEGG analysis revealed that the differentially expressed mRNAs were mostly involved in cytokine-cytokine receptor interaction, the JAK-STAT signaling pathway, hypertrophic cardiomyopathy, the prolactin signaling pathway, and type II diabetes mellitus." (PMID 35096054, 2022). "In addition, estrogens along with prolactin are associated with female predisposition to autoimmune and rheumatic diseases, and sex hormones are involved in the upregulation of the expression of higher adiponectin levels that reduces the risk of type 2 diabetes in women." (PMID 30642023, 2019). "This appears to be in accordance with the finding in the present study of low PRL levels in patients with PE and type 2 diabetes." (PMID 29556396, 2018). "Moreover, 152 KEGG pathways were identified, including type II diabetes mellitus, the Fc epsilon RI signaling pathway, and the prolactin signaling pathway." (PMID 40779572, 2025). "This agent could potentially confound the relationship between PRL and type 2 diabetes (only in cross-sectional studies) by reducing the levels of PRL." (PMID 38760578, 2024). "The adjusted risk of developing type 2 diabetes was increased in European men aged between 40 and 80 years with prolactin concentration below 5 ng/mL and was particularly high in individuals with prolactin levels not exceeding 3 ng/mL." (PMID 39456268, 2024). "On the other hand, in cohort studies, low levels of PRL were associated with greater risk of developing type 2 diabetes in women, but not in men." (PMID 38760578, 2024). "In cohort studies, women showed a significant association between low PRL and type 2 diabetes: OR = 1.52 (1.02–2.28) but not men: OR = 1.44 (0.46–4.57)." (PMID 38760578, 2024). "Although we did not directly examine association between serum PRL levels and type 2 diabetes, we evaluated association between serum PRL levels and HOMA indices, which seem to be surrogate markers for type 2 diabetes, and found positive association between serum PRL levels and HOMA-R in men." (PMID 28384295, 2017). "Furthermore, plasma prolactin levels were found to be significantly decreased in the GK rat, an inbred model of type 2 diabetes." (PMID 24628878, 2014). "The relationship between PRL and type 2 diabetes reported in primary papers were mostly adjusted for confounding factors such as age, body mass index and smoking status, except one study where crude OR was calculated from the reported prevalence of type 2 diabetes." (PMID 38760578, 2024). "On the other hand, low PRL did not predict type 2 diabetes amongst men in cohort studies: OR = 1.44 (0.46–4.57)." (PMID 38760578, 2024).
type 2 diabetes (continued). "PRL within the biologically normal range may play a protective role in the BMD of type 2 diabetes in men rather than in women." (PMID 36313749, 2022). "However, whether either of the two drugs can reduce PRL levels in patients with long-term hospitalized chronic schizophrenia with co-morbid type 2 diabetes (T2DM) has not been adequately reported." (PMID 36816406, 2023).